FTO (FTO alpha-ketoglutarate dependent dioxygenase)
Diseases named in the same sentence as FTO in open-access papers (continued):
Sharing a sentence is not in itself a finding about the gene and the disease.
pancreatic cancer (continued). "Notably, shRNA-mediated perturbation of FTO in pancreatic cancer cells led to alterations in multiple biologically relevant processes associated with pancreatic carcinogenesis, for example, loss of cell growth, motility, and invasiveness." (PMID 36497402, 2022). "In pancreatic cancer cells, inhibiting FTO expression reduces cell proliferation by increasing the m6A modification of the 3′ UTR region of platelet-derived growth factor-C (PDGFC) and regulates the degradation of PDGFC at the transcriptional level in an m6A-YTHDF2 dependent manner." (PMID 36358640, 2022). "FTO regulates the proliferation of pancreatic cancer cells by regulating cell cycle progression." (PMID 34246319, 2021). "Overall, rs9939609 in the FTO gene might be a potential biomarker for early diagnosis or gene therapy targeting pancreatic cancer." (PMID 34239358, 2021). "A recent study failed to suggest an association between FTO polymorphism and the increased risk of cancer, even though FTO polymorphism was marginally associated with the occurrence of pancreatic cancer." (PMID 34499008, 2021). "The association between genetic variations in the FTO gene and the risk of pancreatic cancer, however, is not clear." (PMID 23835106, 2013). "Interestingly, FTO may attenuate gemcitabine resistance in Pancreatic cancer by modulating neural precursor cell expressed developmentally downregulated 4 (NEDD4) mRNA stability through the PTEN/PI3K/AKT signaling axis." (PMID 40986143, 2025). "In addition, depletion of FTO led to the compromised proliferation of pancreatic cancer cells." (PMID 35211409, 2022). "However, if FTO has any role in regulating CSC in pancreatic cancer, a significant impediment to successful PDAC treatment remains unknown thus far." (PMID 36497402, 2022). "In addition, stable depletion of FTO led to induction of apoptosis in pancreatic cancer cells." (PMID 36497402, 2022). "To gain more insight into the potential impact of targeting FTO, we employed a PDAC xenograft model with FTO inhibitor treatment to explore the effect of this potential therapy against pancreatic cancer." (PMID 41184232, 2025). "All of the results above indicate that m6A modification mediated by the demethylase FTO and the reader YTHDF2 plays an important role in maintaining the stability of LINC01134 in pancreatic cancer cells as well as relates to the high expression of LINC01134." (PMID 37914721, 2023). "We checked the levels of FTO and ALKBH5 expression in gemcitabine-resistant cells to confirm the function of m6A erasers in controlling gemcitabine chemosensitivity in pancreatic cancer." (PMID 37605223, 2023). "According to the detection of FTO levels in the pancreatic cancer cell lines, we chose CFPAC-1 with the lowest FTO expression level to construct an FTO overexpression model." (PMID 35422475, 2022). "Utilizing a highly selective FTO inhibitor, CS1, we demonstrated the critical impact of FTO inhibition on the cell viability of pancreatic cancer cells and their cell proliferative, motility, and invasive physiognomies." (PMID 36497402, 2022). "Having observed the overexpression of FTO in pancreatic cancer cells, we next intended to determine its role in pancreatic cancer, and hence, we employed a selective pharmacological inhibitor of FTO, CS1, which inhibit FTO’s m6A demethylase activity." (PMID 36497402, 2022). "FTO knockdown markedly increased the PTEN expression level by regulating NEDD4 expression and influenced the PI3K/AKT pathway, which led to chemoresistance to gemcitabine in pancreatic cancer cells." (PMID 37605223, 2023). "FTO knockdown markedly increased the PTEN expression level in an NEDD4-dependent manner and influenced the chemosensitivity to gemcitabine through the PI3K/AKT pathway in pancreatic cancer cells." (PMID 37605223, 2023). "The m6A erasers FTO and ALKBH5 play roles in promoting pancreatic cancer." (PMID 35945641, 2022).
pancreatic cancer (continued). "Notably, FTO inhibition using this pharmacological inhibitor CS1 resulted in a dose- and time-dependent decrease in viability of MiaPaCa2, Panc1, and BxPC3 pancreatic cancer cells." (PMID 36497402, 2022). "Furthermore, pancreatic cancer patients with lower METTL3, METTL14, RBMX, FTO, ALKBH5, YTHDF1, and YTHDC1 mRNA expression levels or higher VIRMA, HNRNPA2B1, EIF3A, IGF2BP1, IGF2BP2, and IGF2BP3 mRNA expression levels had significantly poorer OS (P < 0.05)." (PMID 34330301, 2021). "The overexpression of FTO, IGF2BP2 and YTHDF2 are related to the pancreatic cancer." (PMID 32612834, 2020). "In addition, FTO depletion significantly upregulates PTEN expression in a NEDD4-dependent manner, thereby regulating gemcitabine sensitivity via the PI3K/AKT pathway in pancreatic cancer cells." (PMID 40986143, 2025). "However, the roles of FTO in pancreatic cancer progression are not completely understood." (PMID 35422475, 2022). "Thus, results suggest that the FTO inhibitor acts explicitly on the pancreatic cancer cells that overexpress FTO and remain insensitive to the normal HPDE cells with low FTO expression." (PMID 36497402, 2022).
ovarian carcinoma (44 papers, 2019 to 2025). A malignant neoplasm originating from the surface ovarian epithelium. "Functional assays demonstrated that FTO downregulation was associated with enhanced proliferation, migration, and invasion of ovarian cancer cells, which coincide with elevated global m6A methylation levels." (PMID 41141648, 2025). "Bioinformatics and experimental analyses revealed that the fat mass and obesity‐associated protein (FTO) was significantly downregulated in ovarian cancer tissues and cell lines." (PMID 41141648, 2025). "Overall, this study aimed to elucidate the role and underlying mechanisms of FTO in ovarian cancer development." (PMID 41141648, 2025). "In this study, we investigate the role of FTO (fat mass and obesity‐associated protein), a key demethylase involved in N6‐methyladenosine (m6A) RNA modification, in the progression of ovarian cancer." (PMID 41141648, 2025). "In this study, the authors found that expression of fat mass and obesity associated protein (FTO) increased the sensitivity of ovarian cancer cells to platinum both in vitro and in vivo." (PMID 39272943, 2024). "This study demonstrated for the first time that fat mass and obesity-associated protein (FTO) acts as an m6A demethylase to inhibit epithelial ovarian cancer growth and metastasis." (PMID 36358640, 2022). "Moreover, clinical studies and trials are essential to assess the diagnostic and therapeutic value of FTO and m6A methylation in ovarian cancer, with the ultimate goal of developing more effective and personalized treatment strategies for patients." (PMID 41141648, 2025). "Additionally, a recent study demonstrated that FTO evoked Wnt/β-catenin pathway by stabilizing the frizzled class receptor 10 (FZD10) mRNA in BRCA-mutated epithelial ovarian cancer." (PMID 35211409, 2022). "By uncovering the tumor‐suppressive function of FTO, our study provides a scientific foundation for the development of FTO‐based diagnostic and therapeutic strategies, which may ultimately enhance early detection and treatment outcomes in ovarian cancer." (PMID 41141648, 2025). "This study identifies FTO as a key negative regulator of ovarian cancer progression and highlights the therapeutic potential of targeting the m6A methylation pathway." (PMID 41141648, 2025). "Several studies have reported that FTO has tumour suppressor activity, and its expression is inversely correlated with the progression of ovarian cancer, hepatocellular carcinoma, intrahepatic cholangiocarcinoma, and renal cell carcinoma." (PMID 40621649, 2025). "Bioinformatics analysis of public datasets, along with validation in clinical samples, revealed that FTO expression was significantly lower in ovarian cancer tissues compared to normal controls." (PMID 41141648, 2025). "Based on our results, several conclusions can be drawn: FTO expression is significantly downregulated in ovarian cancer tissues compared to normal controls, and this reduction is closely associated with increased cell proliferation, migration, and invasion." (PMID 41141648, 2025). "Our current findings support a tumor‐suppressive function of FTO in ovarian cancer, consistent with the context‐dependent behavior reported in other malignancies." (PMID 41141648, 2025). "In summary, our findings indicate that FTO expression is significantly downregulated in ovarian cancer cells, contributing to elevated m6A methylation levels." (PMID 41141648, 2025). "Collectively, these results demonstrate that FTO suppresses ovarian cancer progression in vivo by increasing m6A methylation and the expression of proliferation‐associated proteins, particularly Ki67." (PMID 41141648, 2025). "Both mRNA and protein levels of FTO were significantly reduced in ovarian cancer tissues and SKOV3 cells compared to controls." (PMID 41141648, 2025).
ovarian carcinoma (continued). "Our results demonstrated that FTO expression was significantly downregulated in ovarian cancer samples compared to normal controls and was strongly associated with increased cellular proliferation, migration, and invasion." (PMID 41141648, 2025). "The scientific and clinical significance of this study lies in its identification of FTO as a key regulator of m6A methylation and tumor growth in ovarian cancer." (PMID 41141648, 2025). "Overexpression of FTO markedly inhibits tumorigenic behavior both in vitro and in vivo, whereas FTO knockout promotes ovarian cancer progression." (PMID 41141648, 2025). "Our findings not only corroborate the dysregulation of FTO in ovarian cancer but also build upon existing knowledge by clarifying its association with m6A methylation levels and oncogenic behaviors such as cell proliferation, migration, and invasion." (PMID 41141648, 2025). "In conclusion, our study highlights FTO as a critical epitranscriptomic regulator and a potential biomarker and therapeutic target in ovarian cancer." (PMID 41141648, 2025). "The primary aim of this study was to explore the diagnostic value of peripheral blood m6A methylation levels in ovarian cancer and to elucidate the molecular mechanisms involving the RNA demethylase FTO." (PMID 41141648, 2025). "Using bioinformatics analyses of transcriptomic data derived from ovarian cancer patients and normal controls in publicly available databases such as TCGA and GEO,20, 21, 22 we identified FTO as a significantly DEG in ovarian cancer." (PMID 41141648, 2025). "From a broader perspective, future research should aim to clarify the regulatory mechanisms of FTO and m6A methylation in ovarian cancer progression and explore their interactions with other signaling networks." (PMID 41141648, 2025). "This research provides novel insights into the epitranscriptomic regulation of ovarian cancer and lays the groundwork for FTO‐based therapeutic development." (PMID 41141648, 2025). "We also examined the subcellular localization of FTO and its correlation with ovarian cancer cell proliferation." (PMID 41141648, 2025). "Through in vivo experiments using a murine xenograft model, we further validated the tumor‐suppressive role of FTO in ovarian cancer development." (PMID 41141648, 2025). "Together, these findings highlight FTO as a critical negative regulator of ovarian cancer progression and underscore the potential of targeting m6A methylation pathways as a therapeutic target." (PMID 41141648, 2025). "Although previous studies have suggested a role for FTO in various cancers, its specific function in ovarian cancer remains incompletely understood." (PMID 41141648, 2025). "FTO significantly influences the progression of ovarian cancer by impairing the self-renewal processes of ovarian stem cells and interfering with the cAMP signaling cascade through its function as a demethylation enzyme." (PMID 39175477, 2024). "FTO inhibits ovarian cancer stem cell self‐renewal by upregulating PDE1C and PDE4B, which subsequently block the cAMP signalling pathway." (PMID 38545841, 2024). "In epithelial ovarian cancer cells harboring a BRCA1/2 gene mutation, downregulation of FTO can enhance the stability of FZD10 mRNA via m6A modification, leading to elevated expression of FZD10 protein." (PMID 39175477, 2024). "Research indicates a significant downregulation of FTO expression in ovarian cancer, as highlighted by several studies." (PMID 39175477, 2024). "The role and impact of FTO within ovarian cancer contexts present ongoing subjects of debate among researchers." (PMID 39175477, 2024). "In epithelial ovarian cancer (EOC), increased m6A levels were associated with decreased FTO expression." (PMID 39175477, 2024).
ovarian carcinoma (continued). "At present, there remains a lack of consensus within the medical research community concerning the specific influence of FTO on the diverse pathological subtypes of ovarian cancer." (PMID 39175477, 2024). "Numerous studies have presented conflicting views regarding FTO’s role in the diverse pathological manifestations of ovarian cancer." (PMID 39175477, 2024). "Consistent with our results, IGF2BP2 and IGF2BP3 were significantly increased in ovarian cancer, whereas FTO was significantly decreased in ovarian cancer." (PMID 38714753, 2024). "In various ovarian cancer studies, the erasers FTO and ALKBH5 regulate various biological processes." (PMID 37194218, 2023). "Overexpression of FTO increased the survival and autophagy of ovarian cancer cells but decreased apoptosis." (PMID 37007161, 2023). "In contrast to the tumor-promoting function of FTO previously reported in other types of cancers, FTO performs a tumor-suppressive role in ovarian cancer." (PMID 39872957, 2023). "FTO is expressed at low levels in ovarian cancer stem cells (OCSC), and its overexpression inhibits OCSC proliferation, self-renewal and spherogenesis, and blocks cAMP signalling dependent on m6A demethylation." (PMID 37194218, 2023). "Patients with ovarian cancer had low levels of FTO and ALKBH5, whereas those with higher levels of both presented shorter overall survival and progression-free survival (PFS)." (PMID 37194218, 2023). "FTO hindered ovarian cancer stem cell self-renewal by m6A RNA demethylation and inhibited tumor development by suppressing cAMP signaling." (PMID 36718644, 2023). "The abnormal expression of m6A-related regulatory enzymes including METTL3, FTO, ALKBH5, IGF2BP1, YTHDF1, and YTHDF2 is closely linked with the growth, metastasis, invasion, and chemotherapy resistance in ovarian cancer." (PMID 37781028, 2023). "Further, we demonstrated that FTO expression is negatively correlated with the FIGO stage in patients with epithelial ovarian cancer." (PMID 36358640, 2022). "We then carried out bioinformatic analyses for further verification of FTO expression in ovarian cancer." (PMID 36358640, 2022). "Recently, studies have showed that FTO can constrain ovarian cancer stem cells by promoting the decay of PDE1C and PDE4B mRNA." (PMID 35397614, 2022). "The downregulation of FTO and ALKBH5 in ovarian cancers with breast-cancer susceptibility gene 2 (BRCA2) mutations enhanced FZD10 mRNA m6A modifications, which ultimately reduced the sensitivity of PARPi via the Wnt/β-catenin pathway." (PMID 36517820, 2022). "In another study, FTO downregulation led to an increase of the m6A abundance, and overexpression of FTO suppressed the self-renewal of ovarian cancer stem cells." (PMID 35211409, 2022). "In ovarian cancer cells, FTO overexpression significantly reduced apoptosis and promoted AKT phosphorylation." (PMID 35563339, 2022). "We then infected ovarian cancer cells with an FTO overexpression lentivirus to construct stably transfected cell lines." (PMID 36358640, 2022). "TCGA and GTEX database analyses showed that FTO mRNA expression was decreased in ovarian cancer patients, and the CPTAC database showed that FTO protein levels were also decreased in ovarian cancer patients." (PMID 36358640, 2022). "Meanwhile, several studies have reported that FTO has tumor suppressor activity and is inversely correlated with tumor progression in ovarian cancer, hepatocellular carcinoma, intrahepatic cholangiocarcinoma and renal cell carcinoma." (PMID 34218271, 2021). "FTO overexpression inhibited the proliferation and tumorigenesis of OCSCs, and the deletion of FTO in ovarian cancer cells led to an increase in m6A levels, which induced cancer cells proliferation and colonies formation and promoted a CSC phenotype." (PMID 34794452, 2021). "Experiments have revealed that the expression of FTO was appreciably lower in OC cells and OCSCs than in normal ovarian cancer tissues." (PMID 34794452, 2021).